MAP7D1 (MAP7 domain containing 1)
Description:
Microtubule-stabilizing protein involved in the control of cell motility and neurite outgrowth. Facilitate microtubule stabilization through the maintenance of acetylated stable microtubules.
Synonyms: PARCC1; RPRC1; FLJ10350; FLJ39022
Tractability: PROTAC: UniProt records ubiquitination sites on it; ubiquitination databases record sites on it; its protein half-life has been measured.
Gene: Protein-coding gene on chromosome 1 (36,155,579 to 36,180,849, forward strand). Ensembl gene ENSG00000116871.
Subcellular location: Cytoplasm, cytoskeleton, spindle; Cytoplasm, cytoskeleton; Cytoplasm, cytoskeleton, microtubule organizing center, centrosome; Midbody
Gene Ontology:
Biological process: microtubule cytoskeleton organization
Cellular component: spindle; centrosome; microtubule cytoskeleton; midbody; cytoskeleton
Genetic constraint (gnomAD): Loss-of-function variants: 30 observed, 69.47 expected, observed/expected ratio (o/e) 0.43, 90% interval 0.32 to 0.59. The synonymous counts are far from expectation, so gnomAD's model fits this gene poorly and the ratio says little. Missense variants: 1,123 observed, 998.95 expected, observed/expected ratio (o/e) 1.12, 90% interval 1.07 to 1.18. Synonymous variants: 514 observed, 402.34 expected, observed/expected ratio (o/e) 1.28, 90% interval 1.19 to 1.37.
Homologues: Orthologues: macaque MAP7D1 (97% identical), chimpanzee MAP7D1 (93% identical), pig MAP7D1 (90% identical), rabbit MAP7D1 (88% identical), mouse Map7d1 (87% identical), rat Map7d1 (87% identical), guinea pig MAP7D1 (80% identical), tropical clawed frog map7d1 (51% identical), zebrafish map7d1a (43% identical), zebrafish map7d1b (38% identical), Drosophila melanogaster ens (24% identical), zebrafish si:ch73-281i18.7 (7% identical), and 3 more. Paralogues in human: MAP7 (31% identical), MAP7D2 (25% identical), MAP7D3 (20% identical).
Diseases named in the same sentence as MAP7D1 in open-access papers:
MAP7D1 is named in the same sentence as 19 diseases in open-access papers, as found by Europe PMC text mining. Sharing a sentence is not in itself a finding about the gene and the disease. The quoted sentences say what the papers report.
breast carcinoma (2 papers, 2021 to 2023). "Among genes carrying these metastasis-associated 5hmC signatures, MAP7D1 participates in breast cancer cell proliferation and metastasis." (PMID 33716151, 2021). "Meanwhile, the role of MAP7D1 in breast cancer progression suggests that the metastasis-associated 5hmC signatures are potential biomarkers to predict the risk for lymph node metastasis, which may serve as diagnostic and therapeutic targets for metastatic breast cancer." (PMID 33716151, 2021). "Furthermore, the role of MAP7D1 in breast cancer progression implies a link between 5hmC-mediated epigenetic regulation and lymph node metastasis, thus offering new options to develop diagnostic and therapeutic targets for metastatic breast cancer." (PMID 33716151, 2021). "This study provides evidence in vitro and in vivo that MAP7D1 promotes breast cancer cell proliferation and metastasis both in vitro and in vivo." (PMID 33716151, 2021). "While its homologue MAP7D3 promotes breast cancer growth and metastasis in mice, the role of MAP7D1 in cancer metastasis remained unclear yet." (PMID 33716151, 2021). "To evaluate the in vivo effect of MAP7D1 on tumor growth and metastasis, we established an orthotopic breast cancer mouse model using MCF7 cells overexpressing MAP7D1 or MDA-MB-231 cells with MAP7D1 knockdown." (PMID 33716151, 2021). "We further investigated the biological functions of MAP7D1 in metastatic processes of breast cancer." (PMID 33716151, 2021). "We identified a positive correlation between the 5hmC level of MAP7D1 and the metastatic ability of primary tumors and further demonstrated its regulatory effect on breast cancer progression." (PMID 33716151, 2021). "In addition, high expression levels of MAP7D1 have been also recently shown to promote breast cancer proliferation and metastasis." (PMID 36852271, 2023). "In addition, overexpression of MAP7D1 promoted breast cancer cell migration, while MAP7D1 knockdown impaired its role on cell migration and invasion." (PMID 33716151, 2021). "Moreover, among the four types of breast cancer cell lines with different metastatic abilities, the expression of MAP7D1 was higher in two aggressive cell lines (MDA-MB-231 and MDA-MB-453), and lower in two less aggressive cell lines (MCF7 and T47D)." (PMID 33716151, 2021).
bone marrow failure (1 paper, 2025). "Given that mitotic aberrations are crucial in the development of pathogenic conditions, such as neutropenia, bone marrow failure and pancreatic insufficiency that are important for the etiology of SDS, we propose that the MAP7D1:p.R201W mutation contributes to SDS." (PMID 40856631, 2025).
cardiomyopathy (1 paper, 2021). A disease of the heart muscle or myocardium proper. "Disruption of MAP7D1 gene function would increase the risk of cancer patients to developing cardiomyopathy and heart failure after receiving doxorubicin chemotherapy." (PMID 34327238, 2021). "Together, this study identifies MAP7D1 as a clinically relevant susceptibility gene to DIC and heart failure, providing useful information to stratify cancer patients with a high risk of incurring severe cardiomyopathy and heart failure after receiving chemotherapy." (PMID 34327238, 2021).
congestive heart failure (1 paper, 2023). Failure of the heart to pump a sufficient amount of blood to meet the needs of the body tissues, resulting in tissue congestion and edema. "Seventeen patients whose LVEF levels were monitored throughout the clinical trial experienced irreversible congestive heart failure (CHF), thus concluding that the decline in LVEF and CHF was correlated with the MAP7D1 gene being a susceptible gene to DIC and HF." (PMID 37270590, 2023).
heart failure (1 paper, 2021). Inability of the heart to pump blood at an adequate rate to meet tissue metabolic requirements. "Through analyzing a reported GWAS dataset, we identified 2 variants in the human MAP7D1 gene significantly associated with decline of cardiac function and heart failure in cancer patients who received the doxorubicin chemotherapy." (PMID 34327238, 2021). "To further provide clinical relevance, we analyzed a reported human GWAS dataset conducted in cancer patients who received doxorubicin therapy and identified two MAP7D1 gene variants associated with cardiac function decline and heart failure in humans." (PMID 34327238, 2021). "Lastly, we identified 2 MAP7D1 gene variants associated with cardiac functional decline and heart failure in cancer patients who received doxorubicin therapy." (PMID 34327238, 2021). "Thus, a major novelty of this study is to combine the power of zebrafish genetics and a human GWAS for both identification and functional elucidation of MAP7D1 as a clinically relevant susceptibility gene to DIC and heart failure." (PMID 34327238, 2021).
kidney damage (1 paper, 2022). "TA might be involved in kidney damage, causing TRPV4 dysfunction by decreasing the expression of MAP7D1." (PMID 35477741, 2022).
lymph node metastasis (1 paper, 2021). "Through genome-wide analysis of 8 sets of primary tumors, we identified 100 high-confidence metastasis-associated 5hmC signatures, and it is found that increased levels of DNA 5hmC and gene expression of MAP7D1 associate with high risk of lymph node metastasis." (PMID 33716151, 2021).
male infertility (1 paper, 2024). The inability of the male to effect fertilization of an ovum after a specified period of unprotected intercourse. "Map7d1 facilitates microtubule stabilization and Mfn1 deficiency leads to defects in mitochondrial activity and male infertility." (PMID 38470475, 2024).
neuroblastoma (1 paper, 2022). Neuroblastoma (NB) is the most common solid, extracranial childhood tumor. "We also examined the cellular functions of Map7D2 using the N1-E115 mouse neuroblastoma cell line, which expresses both Map7D2 and Map7D1 but not Map7 nor Map7D3." (PMID 35470240, 2022). "For this experiment, we used a mouse neuroblastoma cell line, N1-E115, in which the expression of Map7d2 and Map7d1, but not Map7 and Map7d3, was detected by quantitative real-time PCR (RT-qPCR)." (PMID 35470240, 2022).
schizophrenia (1 paper, 2025). A major psychotic disorder characterized by abnormalities in the perception or expression of reality. "MAP7D1, predicted to be involved in microtubule cytoskeleton organization, was recently identified to be associated with schizophrenia by a transcriptome-wide association study." (PMID 39948187, 2025).
cardiovascular diseases (1 paper, 2025). "We selected top three proteins, Map7 domain-containing protein 1 (Map7D1) 17, Bcl-2-associated transcription factor 1 (Bclaf1) 18,19 and CPT1b 20,21, which were closely related to cardiovascular diseases, for further investigation." (PMID 40093901, 2025).
tumor (1 paper, 2021). "Together, we provide strong evidence here that MAP7D1, one of the representative genes containing metastasis-associated 5hmC signatures, promotes tumor growth and metastasis." (PMID 33716151, 2021). "Compared to the control group, MAP7D1 overexpression significantly promoted tumor growth, while MAP7D1 knockdown led to reduced tumor volume and weight." (PMID 33716151, 2021). "Furthermore, we demonstrate that MAP7D1, regulated by TET1, promotes tumor growth and metastasis." (PMID 33716151, 2021).
MAP7D1 also shares sentences with these, for which no sentence is quoted: cancer (4 papers); gastric cancer (1); glioblastoma (1); neutropenia (1); pancreatic insufficiency (1); renal carcinoma (1); Shwachman-Diamond syndrome (1).